STAT3 (signal transducer and activator of transcription 3)
Diseases named in the same sentence as STAT3 in open-access papers (continued):
Sharing a sentence is not in itself a finding about the gene and the disease.
colitis (continued). "In the DSS-induced colitis model, inhibition of NF-κB and STAT3 activities ameliorated colonic inflammation by downregulating pro-inflammatory proteins." (PMID 36286060, 2022). "PHD2 expression (i) reduces the number of TAMs in AOM/DSS tumors, (ii) impairs the protumorigenic properties of macrophages at least in part through decreased Ereg expression, and (iii) diminishes STAT3 and ERK1/2 signaling in colitis-associated tumors." (PMID 36509284, 2022). "Conversely, in the MLN, there was an increased frequency of Ly5.1+ cells used to induce colitis and a corresponding decreased frequency of Ly5.1– cells in mice treated with STAT3 GOF Tregs." (PMID 36136607, 2022). "Experimental observations suggest that the expression of MIR31, phosphorylated p65 (p-65), and phosphorylated STAT3 (p-STAT3) present an “adaptation” behavior in dextran sulfate sodium (DSS)-induced mouse colitis, which are well reproduced by our model." (PMID 36590397, 2022). "STAT3 has been found to contribute, with contrasting effects, to colitis in three cell lineages (myeloid cells, enterocytes, and T cells) in mice and humans." (PMID 36498596, 2022). "Curcumin can exert an anti-inflammatory effect in experimental colitis by inhibiting the STAT3 pathway." (PMID 35979355, 2022). "Simulation analysis predicts MIR31 suppresses the activation of p65 and STAT3 but accelerates the recovery of epithelia in colitis, which are validated by our experimental observations." (PMID 36590397, 2022). "Conversely, inhibition of NF-κB and/or STAT3 signaling pathways has been reported to reduce pro-inflammatory cytokines and inflammation response in colitis." (PMID 36079868, 2022). "To directly assess the contribution of STAT3 in the P2RY13-induced exacerbation of colitis,we used the Flox-villin-Cre system to delete STAT3 from intestinal epithelium of mice." (PMID 35982893, 2022). "For example, an intriguing dichotomy exists with the STAT3 signaling pathway: its activation in IECs253, 254 or IMφs255 is thought to be anticolitic, whereas its activation in T cells exacerbates colitis." (PMID 35593111, 2022). "We also detected increased p-Stat3 levels in the samples of colitis mice, which was suppressed by BBR." (PMID 36528592, 2022). "Pretreatment with compounds 7b and 13b alleviated the severity of colitis and concomitantly counteracted the increased levels of RORγt, STAT3, CCR6, IL-6, IL-17, IL-23, TNF-α, and PGE2." (PMID 36077306, 2022). "Consistent with that, the western blotting results showed that phosphorylation levels of JAK2 and STAT3 were significantly increased in DSS-induced colitis mice, and MOP administration reversed this trend." (PMID 35911761, 2022). "Many polysaccharides from TCMs have been demonstrated to inhibit the IL-6/STAT3 pathway in DSS-induced colitis mice." (PMID 36341374, 2022). "The Western blotting results showed that the level of STAT3 in colonic tissue increased in colitis mice and decreased after PAMK treatment." (PMID 36341374, 2022). "We also found support for Stat3 in sex-specific regulations of both an HFD-induced colitis model and in a paired human CRC and normal colon comparison." (PMID 36142324, 2022). "A recent study suggested that the protective effects of leptin on tight-junction proteins and mucosal barrier function in a DSS-induced mouse colitis model were partly mediated by STAT3 phosphorylation." (PMID 35888062, 2022). "Nrf2 activation followed by STAT3 signaling pathway play a pivotal role in the protective effect of SFN on colitis." (PMID 35832050, 2022). "El-Mahdy and his workmates reported that mesalazine can enhance anti-inflammatory effects to attenuate progression of oxazolone-induced colitis by restoring IL-10 and ZO-1 levels and limiting IL-6/STAT-3 trans-signaling." (PMID 35388299, 2022). "The improved expression of colonic cytokines, JAK2, and STAT3 was closely related to the severity of DSS-induced colitis." (PMID 36312760, 2022).
colitis (continued). "Combined with the observation that KLF5 was lower in active UC, results of these experiments implicate a role for KLF5 in modulating p-STAT3 signaling in human colitis as well." (PMID 35393949, 2022). "Our study indicates that MIR31 exhibits an “adaptation” behavior in WT model of DSS-induced colitis and similar “adaptation” behavior also occurs in p-p65 and p-STAT3." (PMID 36590397, 2022). "The immunohistochemical evaluation showed that induction of colitis increased the expression of RORγt, STAT3, and CCR6 in the colon tissues compared to the control group (p < 0.01, p < 0.01, p < 0.001, respectively)." (PMID 36077306, 2022). "Level of MIR31 presents an “adaptation” behavior in dextran sulfate sodium (DSS)-induced colitis, and the similar behavior is also observed for the key cytokines of p65 and STAT3." (PMID 36590397, 2022). "The results showed that the increased expression of p-P65 and p-STAT3 in experimental colitis was significantly blocked upon PNU-282987 treatment." (PMID 36058917, 2022). "In IBD patients and some animal models with colitis, there are high levels of IL-6 expression and high levels of STAT3 phosphorylation, which are related to disease activity." (PMID 35982893, 2022). "The activity of the oncogenic STAT3 and ERK1/2 signaling pathways is increased in colitis-associated Phd2+/– tumors." (PMID 36509284, 2022). "Then the results of FISH assays showed that the levels of mmu_circ_001109, p‐STAT3 and p‐P65 were significantly up‐regulated in both DSS‐induced colitis and AOM/DSS‐associated CAC groups, compared to the NC group." (PMID 35184406, 2022). "Deletion of the STAT3 gene in the intestinal epithelial cells of mice significantly mitigated the exacerbation of colitis due to P2Y13 activation." (PMID 35982893, 2022). "DSS-stimulated colitis rats showed a clear trend of upregulation of p-NF-κB p65, p-STAT3 and p-JAK2 proteins, all of which were downregulated in rats treated with three treatments (P < 0.05,P < 0.01 or P < 0.001)." (PMID 36424592, 2022). "In summary, STAT3 GOF Tregs improved survival in a mouse model of experimental colitis, despite impaired Treg recovery and control of Ly5.1+ T cell accumulation and IL-17A secretion." (PMID 36136607, 2022). "Another study reported that the upregulation of the STAT3 signaling pathway is related to mucus secretion in mice with experimental colitis." (PMID 36590229, 2022). "We further constructed a STAT3 inhibition model with Stattic in acute colitis, and found that the inactivation of STAT3 abrogated the anti-inflammatory effect by L. johnsonii." (PMID 36398889, 2022). "In this present study, the expression of STAT3 in the DSS-induced colitis mice was markedly decreased and significantly elevated when treated with SFN." (PMID 35832050, 2022). "In conventionally housed IL-37tg mice with DSS induction, IL-37 receptors Il-18r1 and Il1rapl1 mRNA levels and additional downstream signaling pathway genes (Jun, Myd88, Sigirr, Smad3, Stat1, and Stat3) were expressed similarly as in control WT colitis mice." (PMID 35836813, 2022). "It reduces the severity of dextran sulfate sodium (DSS)-induced colitis by blocking the DNA binding of STAT3 and suppressing STAT3 phosphorylation in the mouse colon." (PMID 34068714, 2021). "We found previously that gut-specific disruption of murine Sgpl1 results in sensitivity to colitis due to Stat3 activation." (PMID 33755599, 2021). "Increased STAT3 phosphorylation at tyrosine residues is found in the murine dextran sulphate sodium- (DSS-) induced colitis model, as well as in the epithelial tissue and lamina propria cells of IBD patients." (PMID 34211567, 2021). "Together, these findings demonstrate that IL-6ST/gp130/STAT3 activation plays a prominent role in regulating intestinal barrier function during colitis." (PMID 33673239, 2021). "Previous studies in a mouse model of colitis have demonstrated that mice with IEC-specific deletion of Stat3 display increased IL-6 expression." (PMID 33673239, 2021).
colitis (continued). "T cell-specific knockout of STAT3 ameliorates DSS-induced colitis by reducing the inflammatory response." (PMID 33967779, 2021). "In this study, we attempted to determine the role of miR‐223 in dextran sodium sulfate (DSS)‐induced colitis and explore the involvement of the IL‐6/STAT3 pathway in the development of intestinal mucosal inflammation." (PMID 33332758, 2021). "The colon tissue from DSS-induced SMILE transgenic colitis mice showed increased levels of SMILE and AMPK and decreased levels of mTOR and STAT3 compared to the colon tissue of wild-type DSS-induced colitis mice." (PMID 34211461, 2021). "To investigate the functional role of IL-6ST/gp130-dependent STAT3 during colitis development, we induced acute colonic injury and inflammation by administration of DSS via drinking water." (PMID 33673239, 2021). "Curcumin is reported to exert therapeutic effects in experimental colitis induced by dextran sulfate sodium (DSS) through blocking STAT3 signaling pathway." (PMID 34337082, 2021). "Curcumin can alleviate the severity of colitis by suppressing the expression of STAT3, NF-κB, COX-2, and iNOS." (PMID 34337082, 2021). "Our study indicates that IL-6ST/gp130/STAT3 signalling is critical in promoting intestinal barrier function and epithelial regeneration during colitis." (PMID 33673239, 2021). "Collectively, our findings suggest that a reduction in IL-6ST/gp130-dependent STAT3 activity results in dysregulated expression of tight junction proteins, thereby impairing barrier function to increase susceptibility to DSS-induced colitis." (PMID 33673239, 2021). "The levels of activated STAT3 in T-cells, epithelial cells and macrophages, have been shown to directly correlate with the severity of colitis." (PMID 33959000, 2021). "In this study, we demonstrated that DOK3 plays a protective role in experimental colitis by restraining JAK2/STAT3 signaling in colonic neutrophils in response to commensal microbes." (PMID 34743196, 2021). "In DSS-induced colitis mice, allicin reduced colon damage by suppressing the phosphorylation of STAT3 and inhibiting the expression of NF-κB." (PMID 34068714, 2021). "In mice models of colitis associated cancer, SOCS3 deletion in intestinal epithelial cells (IEC) exacerbated the development of cancer through constitutive STAT3 activation leading to IEC proliferation." (PMID 34604264, 2021). "STAT3 has been reported to be highly phosphorylated in IBD patients and to be further involved in colitis-associated cancer as well as colonic inflammation." (PMID 34068714, 2021). "The upregulation of miR‐223 by agomir administration alleviated colonic inflammation in a DSS‐induced colitis model, which was likely mediated by inhibiting the production of pro‐inflammatory cytokines via the IL‐6/STAT3 signaling pathway." (PMID 33332758, 2021). "Meanwhile, the combination can reduce the release of pro-inflammatory cytokines by inhibiting the MAPK, NF-κB, and signal transducer and activator of transcription 3 (STAT3) signaling pathways in the DSS-induced colitis." (PMID 34966755, 2021). "This study explored the potential role of miR‐223 in dextran sodium sulfate (DSS)‐induced colitis and its involvement in the IL‐6/STAT3 pathway during the pathogenesis of colitis." (PMID 33332758, 2021). "In conclusion, this study suggested that PF-04447943 ameliorates DSS-induced colitis by prohibiting oxidative stress and inflammation by activating Nrf-2 and modulating NF-kB, STAT3, and inflammasome activity." (PMID 33967779, 2021). "The key role of Stat3 signal transduction in inflammation has been demonstrated in colitis-related mouse models." (PMID 33777833, 2021). "In the present study, two mouse models were utilised to examine the significance of IL-6ST/gp130-dependent activation of STAT3 in intestinal barrier function during colitis." (PMID 33673239, 2021).
colitis (continued). "Metformin also increased the level of SMILE and suppressed that of mTOR and STAT3 in colon tissue of DSS-induced compared to vehicle-treated DSS-induced colitis mice." (PMID 34211461, 2021). "Taken together, these results suggest that TauCl exerts the protective effect against colitis through upregulation of Nrf2-dependent cytoprotective gene expression while blocking the proinflammatory signaling mediated by NFκB and STAT3." (PMID 33803551, 2021). "A reduction in STAT3 activity resulted in more severe colitis and impaired epithelial proliferation." (PMID 33673239, 2021). "In comparison to IL-10 and IL-22, we observed that IL-6 was the most abundantly produced cytokine during DSS-induced colitis development in wild-type mice as well as in mice with reduced STAT3 activity." (PMID 33673239, 2021). "Diallyl trisulfide (DATS) is an organic polysulfide from garlic that has been reported to ameliorate disease symptoms in DSS-induced colitis mice by blocking the DNA binding and phosphorylation of STAT3." (PMID 34068714, 2021). "Previous studies have demonstrated that STAT3 confers a protective effect during acute colitis by sustaining proliferation and promoting a wound healing response." (PMID 33673239, 2021). "Our study provides a rationale to exploit upstream activators of IL-6ST/gp130 to induce transient STAT3 activity to maintain barrier integrity and ameliorate colitis in IBD patients." (PMID 33673239, 2021). "Intriguingly, the STAT3 also regulates the differentiation of Th17 cells in colitis, impairs the Treg/Th17 cells balance." (PMID 33967779, 2021). "A gene set enrichment analysis of the intestinal stem cell gene signature in STAT3-deficient and -sufficient mice with DSS colitis, reinforced these results under in vivo tissue-destructive conditions." (PMID 33869257, 2021). "We therefore believe that a comparison between doxycycline-treated and doxycycline-naive shStat3 mice is a relevant comparison to assess the effects of reduced STAT3 activity on DSS-induced colitis." (PMID 33673239, 2021). "In the present study, we used two complementary mouse models to formally align the cellular mechanisms involved in colitis development to STAT3 activity." (PMID 33673239, 2021). "A recent study showed that EGCG downregulated cytokine IL-6 and reduced the expression of STAT3 protein in the colon tissue of colitis-induced mice." (PMID 34068714, 2021). "A previous study has demonstrated that the production of cytokines such as IL-1ɑ, IL-6, IL-10, and IFN-γ are significantly reduced in mice with enhanced STAT3 activity during DSS-induced colitis." (PMID 33673239, 2021). "Our data indicate that IL-6-mediated IL-6ST/gp130 signalling drives STAT3 activation, by which STAT3 modulates intestinal permeability through the expression of tight junction proteins during the development of colitis." (PMID 33673239, 2021). "In a - DSS-induced colitis model, baicalein downregulated the mRNA expression of STAT3/4 in the JAK-STAT signaling pathway in T cells, facilitating its mediation of T cell proliferation." (PMID 33995078, 2021). "Cocoa phenolic compounds exhibited an anti-inflammatory effect decreasing the expression of TNF-α, IL-17, and STAT3 in colonic tissues during DSS colitis." (PMID 33299531, 2020). "In colitis, continued stimulation of IL-6 activates STAT3 signaling, and is prone to modulating the Th17/Treg immune balance owing to Th17 responses." (PMID 33092149, 2020). "In conclusion, we have demonstrated distinct roles of IL-17A and IL-17F in DSS-induced colitis mice model which was dependent on increased Arg-1 secreted by MDSC after ESR/STAT3 activation." (PMID 32391010, 2020). "Although several studies demonstrated that polyphenols exhibited a strong attenuating effect against colitis, there are only a few papers concerning the effect of polyphenols on the IL-23/IL-17 axis and STAT3 expression in experimental colitis." (PMID 33299531, 2020).
colitis (continued). "Although this was not consistent with the mainstream finding regarding the STAT3 signaling pathway in UC, STAT3 would be activated and p-STAT3 would be upregulated in colitis tissues." (PMID 32762699, 2020). "Together, these findings demonstrate a protective role of MDSC-derived Arg-1 during colitis after activates ESR/STAT3 signaling in MDSC." (PMID 32391010, 2020). "Western blot analysis showed that p-STAT3 expression was significantly decreased in the colon tissues of the colitis + TOE group." (PMID 33092149, 2020). "Oral administration of boldine attenuates DSS-induced colitis and reduces colonic phosphorylation of STAT3 and NF-κB p65 subunit as well as the expression of TNFα, IL-6, and IL-17." (PMID 32855621, 2020). "The goal of the present study was to investigate the effects of TAK-242 on the gut microbiota and the TLR4/JAK2/STAT3 signaling pathway in mice with dextran sulfate sodium (DSS)-induced colitis." (PMID 32762699, 2020). "Based on the results of this study, it is likely that both NF-κB and STAT3 signaling are involved in the protective effects of CEE on DSS-induced colitis." (PMID 32059355, 2020). "The proteins and mRNA of JAK2/STAT3 were significantly upregulated, while phosphorylation of JAK2 and STAT3 was downregulated in DSS-induced colitis mice." (PMID 32762699, 2020). "Taken together, these results suggest the activation of the IL-6/STAT3 pathway in Ch25h−/− mice compared with WT mice upon DSS-induced colitis." (PMID 32859970, 2020). "Perhaps, TS suppressed inflammatory cytokines partly via inactivating STAT3 in DSS-induced colitis mice." (PMID 33363184, 2020). "Quercetin effectively stimulated MDSC in DSS-induced colitis mice by activating ESR/STAT3, accompanied by higher Arg-1 and iNOS production." (PMID 32391010, 2020). "The expression of p-STAT3 was significantly decreased in colitis, and berberine hydrochloride had a protective effect by inducing the expression of p-STAT3." (PMID 32762699, 2020). "Sodium propionate administration through oral route reduced the symptoms of DSS-induced colitis by promoting intestinal barrier function and suppressing inflammation and oxidative stress through STAT3 pathway." (PMID 33122795, 2020). "Our previous report found that blocking STAT3 activity was beneficial for murine DSS colitis and also abolished nicotine's protective effect." (PMID 32153570, 2020). "In a recent study, STAT3 was activated in many patients with IBD and increased STAT3 was directly correlated with the severity of colitis and contributed substantially to colitis." (PMID 33092149, 2020). "In this study, we found that the beneficial effect of CEE on DSS-induced colitis is related to inhibition of inflammatory mediators by inactivating NF-κB and STAT3 signaling, and our results suggest a new method for treating or preventing UC." (PMID 32059355, 2020). "Here, we showed that miR-125a and miR-125b in exosomes derived from MSCs targeted on Stat3 to inhibit Th17 differentiation, then resulted in alleviating the symptoms of colitis in mice." (PMID 32733020, 2020). "During ETBF-induced colitis, it activates both STAT3 and Th17 immune response in the colonic mucosa." (PMID 32863742, 2020). "Induction of colitis caused a decrease in intestinal Muc2 and TFF3 mRNA levels and an increase in STAT3 mRNA expression as compared to the control group (p < 0.01, p < 0.05, and p < 0.01, respectively)." (PMID 33299531, 2020). "In DSS-induced colitis, STAT3 phosphorylation was significantly increased in the colon tissue of Gadd45β-KO mice compared to that of WT mice, while active PKB phosphorylation in colon tissue was not altered by Gadd45β." (PMID 31666502, 2019). "Together, these results revealed an important role of tRXRα in modulating inflammatory microenvironment and cytokine production, which likely accounts for its activation of STAT3 during colitis." (PMID 30931933, 2019).